EGF (epidermal growth factor)
Diseases named in the same sentence as EGF in open-access papers (continued):
Sharing a sentence is not in itself a finding about the gene and the disease.
cancer (continued). "In vitro experiments showed that 111In-EGF-Au-PEG targets EGFR-positive cancer cells (MDA-MB-468): >11% of radioactivity was internalised after incubation for 4 h." (PMID 29071190, 2017). "Otherwise, the attenuation of ERK signaling by depleting epidermal growth factor (EGF) inhibits anti-migration of cancer cells." (PMID 28286419, 2017). "The proliferation of residual cancer cells after combined treatment was much lower than that of control and EGF groups, and lower than that of 5-FU group slightly." (PMID 29108242, 2017). "Cardiotoxin III (CTX-III), a membrane toxin from Taiwan cobra (Naja naja) venom, inhibits the migration of cancer cells by reversion of EGF- and HGF-induced EMT." (PMID 29189742, 2017). "And angiogenesis causing up-regulated expression of the vascular endothelial growth factor (VEGF) on human cancer cells by it's ligands such as EGF and TGF-α can also be a factor to induce resistance to EGFR blocking agents." (PMID 28445134, 2017). "We have previously synthesised epidermal growth factor (EGF)-tagged gold (Au) NP (i.e. 111In-EGF-Au) which were designed for the molecular radiotherapy of EGF receptor (EGFR)-positive cancer." (PMID 29071190, 2017). "This concentration of EGF is considerable and widely used in human cancer cell research, and is relevant to those used in the in vitro studies of E. multilocularis and S. mansoni." (PMID 28241017, 2017). "The cancer cell receives a signal (i.e. EGF) which activates a cascade leading to invadopodium formation." (PMID 28938008, 2017). "CIMAvax-EGF vaccine exerts its anti-cancer activity by targeting the immune system, inducing anti-EGF antibodies that result in the decline of the circulating EGF in sera." (PMID 28348561, 2017). "This, in turn, significantly decreases the probability that the remaining EGF binds to its receptor (EGFR) on the surface of cancer cells." (PMID 28348561, 2017). "In this process, TAMs secrete epidermal growth factor (EGF) to activate the EGF receptor on cancer cells, and enhance their motility and invasive potential by increasing invadopodium formation and ECM degradation." (PMID 28883015, 2017). "We previously reported that EGF treatment reduces radiation-induced damage, including oral mucositis, radio-dermatitis, ulcers, and intestinal mucosal damage in cancer patients and rodent models to improve healing." (PMID 27935858, 2017). "The second study used E. coli protoplast-derived nanovesicles engineered to express the epidermal growth factor (EGF) receptor on their surface as a novel treatment against cancer." (PMID 28621731, 2017). "TAMs stimulate cancer cell proliferation by secreting growth factors, e.g., epidermal growth factor (EGF) and platelet derived growth factor (PDGF)." (PMID 28178994, 2017). "All marker levels were found significantly different between healthy controls and cancer subjects (Mann-Whitney U test, P = 0.002 for EGF, sCD26, CAL, MMP-9, CEA and CYFRA 21.1; P = 0.018 for MMP-1 and MMP-7)." (PMID 28117344, 2017). "We next tested PLIMB by labeling epidermal growth factor receptor (EGFR), a protein with implications in many cancers, before and after binding one of its native ligands, epidermal growth factor (EGF)." (PMID 29021557, 2017). "Hypothetically, aberrantly expressed TRPM7 and dysregulated homeostasis of Mg2+ and Ca2+ in cancer cells modulate the epidermal growth factor (EGF)- or other mitogen-induced signaling pathways." (PMID 28379203, 2017). "Taken together, we suggest that the EGF-conjugated GNP complex coupled with NTP treatment efficiently targets EGFR-expressing cancer cells." (PMID 28887524, 2017). "Squamous A431 carcinoma cells treated with 0.1-0.5 ng/ml of EGF proliferate; cells treated with 1-2 ng/ml EGF growth arrest; and cells treated with 5-10 ng/ml EGF undergo apoptosis within 24h." (PMID 29163826, 2017).
cancer (continued). "Epidermal growth factor (EGF) is first expressed by macrophages and increases the formation of elongated protrusions and cell invasion by carcinoma cells." (PMID 28567162, 2017). "The aim of this study was to clarify how EGF affects the uptake by A431 human carcinoma epithelial cells of PS NPs." (PMID 28629179, 2017). "To study the role of secreted IL10 in the proliferation of cancer cells, we collected the conditioned media of A549 cells treated with EGF in serum-free media for 24 h." (PMID 26956044, 2016). "Growth factors like the epidermal growth factor (EGF) play an important role in promoting cancer development and progression." (PMID 27104520, 2016). "Cancer related pathways were still among the top 10 enrichment pathways in EGF-reversion cells, suggesting the maltransformation tendency after hepatic oval cells experiencing EMT and MET." (PMID 26955393, 2016). "The relationship between STAT3 and EGF is originally found in mouse liver, and is usually observed in cancer/tumorigenesis." (PMID 27096934, 2016). "2-O-Bn-InsP5 is able to inhibit the epidermal growth factor-induced PLCγ1 phosphorylation and activity, ultimately resulting in impaired cancer cell migration and invasion." (PMID 27199173, 2016). "Exposure of cancer cells to EGF modulates the splicing pattern of SYK to promote the pro-survival isoform that is associated with cancer tissues in vivo and EGFR activation also induces Syk phosphorylation." (PMID 26934445, 2016). "The platform had two inputs that can be filled with cell media containing a variety of molecules (e.g., EGF) to enhance or suppress cancer invasion." (PMID 27678304, 2016). "Cancer stem-like cells have been cultured under bFGF (+) EGF (+) and serum-free conditions to investigate their sphere-forming ability." (PMID 27349387, 2016). "This suggested that EGF-dependent cancer pathways were enriched the most in the transcriptome of HBL tumors requiring transplantation." (PMID 27910913, 2016). "Cancer cells secrete TGF-β which increases the activation and proliferation of fibroblasts, while EGF secreted by fibroblasts increases the proliferation of cancer cells." (PMID 27078836, 2016). "EGF-induced nuclear co-localization of phospho-Smad2/3 and Snail and cancer cell migration were inhibited by pretreatment with an ERK1/2 inhibitor, PD98059 and a phospho-Smad2 inhibitor, SB203580." (PMID 27829223, 2016). "Methods to isolate cancer stem-like cells as spheres (tumorspheres) are usually done in serum-free media containing exogenous mitogens such as epidermal growth factor (EGF), basic fibroblast growth factor (bFGF), or both." (PMID 26880969, 2016). "HGF and EGF signaling are often hyperactivated in cancer, culminating in increased motility and invasion." (PMID 27105540, 2016). "Cancer cells not only release EGF, but they also overexpress the EGF receptor (EGFR), which is recognized as the initial, indispensable molecular alteration in pancreatic carcinogenesis." (PMID 27655713, 2016). "Chemoattractants, such as epidermal growth factor (EGF), are aggressive drivers of cancer invasion by activating cell membrane receptors and intracellular pathways that provide guidance and motility cues to the cells." (PMID 27678304, 2016). "The role of growth factors-driven signaling in the pathogenesis of human cancer has long been established for EGF, VEGF and their receptors EGFR and VEGFR." (PMID 27806094, 2016). "We showed significantly enhanced cancer cell invasion in response to a transient gradient of epidermal growth factor (EGF)." (PMID 27678304, 2016). "Through studies examining metabolic contributions to growth factor signaling (data not published), we discovered that monocarboxylate transporters (MCTs) are important factors associated with EGF- and HGF-induced cancer cell motility." (PMID 27127175, 2016). "Due to their relevance in cancer biology, therapeutic targeting of EGF, but also of PI3K/AKT/mTOR pathways, appears a promising treatment strategy." (PMID 27655713, 2016).
cancer (continued). "For example, EGF secreted by endothelial cells can promote cancer metastasis by inducing EMT in head and neck cancers." (PMID 26958807, 2016). "Cetuximab is activated by the ligands of EGF (epidermal growth factor) and transforming growth factor-α, and plays a crucial role in the growth and survival of many types of human cancers." (PMID 26927065, 2016). "While many factors are involved in the progression of GC, aberrant expression of epidermal growth factor receptor (EGFR) and its cognate ligands (e.g. EGF and AREG) is one of the major causes for malignancy progression and cancer formation." (PMID 27713123, 2016). "According to VEGF and FGF-9 elevated EGF expression supports fibrogenesis and the subsequent development of cancer." (PMID 26807786, 2016). "Despite the fact that the epidermal growth factor (EGF) family member ERBB3 (HER3) is deregulated in many cancers, the list of ERBB3-interacting partners remains limited." (PMID 26942872, 2016). "Knockdown of Smad2/3 expression suppressed EGF-induced expressions of Snail, vimentin, fibronectin, and cancer cell invasion, suggesting an acquisition of the mesenchymal and migratory phenotype in less aggressive MCF-7 cells." (PMID 27829223, 2016). "In conclusion, SMAD4 HD is associated with the constitutive activation of the ERK and Wnt/β-catenin signalling pathways, and favors the EGF-induced activation of multiple signalling pathways critical to cancer proliferation and invasion." (PMID 27655713, 2016). "In this study, we have identified for the first time a direct interaction between EGFR and Axl RTKs, with EGF/EGFR-induced activation of Axl as a novel signalling pathway to invasion in cancer cells." (PMID 27775700, 2016). "Tumorsphere cultivation is based on culturing cancer cells onto ultralow attachment surface in serum-free media under the supplementation with growth factors such as epidermal growth factor and basic fibroblast growth factor." (PMID 26527320, 2016). "To elucidate the cancer chemopreventive effects of bakuchiol, we used an EGF-induced cell transformation skin cell model comprised of a soft agar assay and human keratinocytes (HaCaT) and mouse epidermal JB6 P+ cells." (PMID 26910280, 2016). "We utilized the proposed model to specifically assess how exposure to EGF impacts 3D cancer cell invasion through the stroma." (PMID 27678304, 2016). "An EGF/CSF-1 paracrine loop has been documented that requires reciprocal signaling and chemotaxis between both cancer cells and macrophages for motility and invasion of MTLn3 breast cancer cells." (PMID 27256981, 2016). "EGFR ligands implicated in human cancers, include EGF, EREG, amphiregulin (AREG), heparin-bound EGF (HB-EGF) and transforming growth factor alpha (TGFα)." (PMID 26958807, 2016). "We report that in cancer cells, PA cycles back and forth from the cellular membrane to the nucleus, affecting the function of epidermal growth factor (EGF), in a process that involves PPARα/LXRα signaling." (PMID 27256981, 2016). "The abundance of actin filaments with free barbed ends correlates directly with EGF-stimulated membrane protrusion in carcinoma cells." (PMID 27748415, 2016). "EGFR is often constitutively stimulated in cancer cells owing to the binding of ligands such as EGF." (PMID 25723471, 2015). "A paracrine loop involving the production of EGF by macrophages and CSF-1 by cancer cells has been demonstrated." (PMID 26043921, 2015). "Taking into consideration enhanced EGFR expression and a high physiological level of EGF, this confirms interplay between cancer cells and epithelial lung cells in determining cancer development." (PMID 25598217, 2015). "Previous studies revealed that macrophages stimulate breast cancer cell migration and invasion through a paracrine loop involving colony-stimulating factor-1 (CSF-1), produced by cancer cells, and EGF produced by macrophages." (PMID 26043921, 2015).
cancer (continued). "Specifically, CDCP1 localization to membrane lipid rafts was shown to be a prerequisite to invadopodia-mediated cell invasion, and cell migration in an ovarion cancer model required EGF-induced relocalization of CDCP1 to the cell surface." (PMID 26497208, 2015). "Based on the observation that PTX3 expression is essential for EGF-enhanced cancer metastasis, we next clarified the mechanisms involved in PTX3-regulated cell metastasis." (PMID 25797258, 2015). "Because CD151 or its associated LB integrins have been shown to functionally collaborate with EGFR in other cancer types, these highly EGF-responsive cell lines were adopted for subsequent functional analyses." (PMID 26377974, 2015). "The decreased expression of RNF20 enhances the transcriptional effects of EGF, leading to an increase in transformation, migration and metastasis of cancer cells and tumourigenesis." (PMID 26466379, 2015). "Recently, we identified that KITENIN/ErbB4-Dvl2-c-Jun axis is an unconventional EGFR-independent downstream signal of EGF and mediates the invasiveness and tumorigenesis of cancer cells." (PMID 26371759, 2015). "The EGF signaling pathway was tested because EGF paracrine signaling was shown in some models to stimulate cancer cell invasion." (PMID 26317041, 2015). "Dioscin can down regulate EGFR and EGF to inhibit cancer, and also has anti-inflammation activity by regulating JNK signaling pathway." (PMID 25879470, 2015). "Epidermal growth factor receptor (EGFR) is often constitutively stimulated in many cancers owing to the binding of ligands such as epidermal growth factor (EGF)." (PMID 25723471, 2015). "An earlier study showed that Sema4B is phosphorylated at serine 825 in some cancer cell lines stimulated with growth factors such as EGF." (PMID 26464987, 2015). "Epidermal growth factor receptor (EGFR) and its ligand, epidermal growth factor (EGF), are overexpressed in many malignancies, including cancers of the head and neck, breast, kidney, lung, colon, ovary, prostate, brain and spine, pancreas, and bladder." (PMID 25723471, 2015). "Among cancer-related cytokines, Nrg1 is one of the most active members of the epidermal growth factor (EGF)-like family." (PMID 25560389, 2015). "In fact, silencing cancer cell EGFR expression or immunodepletion of EGF from macrophage CM, led to inhibition of motility, and abrogation of cancer cell invasion." (PMID 26043921, 2015). "EGCG treatment alters the lipid rafts of cancer cells and inhibits binding of the ligand epidermal growth factor (EGF) to the EGF receptor (EGFR), which is an RTK as well, and the subsequent receptor dimerization." (PMID 25789501, 2015). "In our previous study, we showed that KITENIN (KAI1 C-terminal interacting tetraspanin) promotes the tumorigenic potential of cancers, and epidermal growth factor (EGF) stimulates KITENIN-mediated AP-1 activation." (PMID 26371759, 2015). "Cancer patients usually have elevated serum level of growth factors, namely, epidermal growth factor (EGF), and transforming growth factor-beta (TGF-b)." (PMID 26474384, 2015). "We previously demonstrated that sialidase NEU3, a key glycosidase for ganglioside degradation, is up-regulated in various human cancers, leading to increased cell invasion, motility and survival of cancer cells possibly through activation of EGF signaling." (PMID 25803810, 2015). "EGF and EGF receptor activation have been shown to be involved in the development and progression of many cancers." (PMID 25730904, 2015). "Firstly, we detected the phosphorylation or expression of signaling molecules induced by EGF in three cancer cell lines over a time course." (PMID 24820097, 2014). "In summary, we showed that the non-nucleoside DNMTi hydralazine attenuates the PCa cell phenotype by disrupting several cancer cell pathways, in particular the EGF pathway in DU145 cells." (PMID 24797896, 2014).
cancer (continued). "The present study aimed at screening the gene profiles of inflammatory factors produced from HCCs regulated by EGF and investigating the potential mechanism involved in cancer cell growth and metastasis." (PMID 24268047, 2014). "Yet, for these human breast carcinoma cells, the EGF/M-CSF paracrine feedback loop was found to be complemented by autocrine M-CSF signaling in the cancer cells." (PMID 25339957, 2014). "Changes in expression levels of EGF and the TGFβ1 can disrupt this homeostasis and promote the cancer progression." (PMID 25909813, 2014). "In this manner highly renal-toxic chemotherapeutics can potentially be covalently bound to large molecular weight “targeting” platforms (e.g. IgG, Fab’, EGF) to increase their utility as a form of systemic anti-cancer therapy." (PMID 25844392, 2014). "Tyrosine kinase inhibitors against the epidermal growth factor have become standard of care in cancers such as NSCLC." (PMID 25279350, 2014). "Cetuximab, a humanized anti-EGF receptor monoclonal antibody used for the treatment of cancer, completely inhibited EGF-induced BRET, and the tyrosine kinase inhibitor tyrphostine AG1024 inhibited insulin effect on PIP3 production." (PMID 24647478, 2014). "A growing body of evidence suggests that EGF regulates multiple biological functions such as cancer cell progression, cell proliferation, and metastasis." (PMID 25122478, 2014). "Cancer cells isolated from ascites show an expression of receptors for bFGF, epidermal growth factor (EGF), and VEGF." (PMID 24591765, 2014). "Together our results not only show that ouabain can inhibit EGF-induced oncogenic signaling, but also reduce EGF-induced cell migration, often a prerequisite for cancer cell metastasis." (PMID 25052069, 2014). "We have previously shown that low dose UVB illumination of cancer cells overexpressing EGFR prior to adding EGF halted the EGFR signaling pathway." (PMID 25386651, 2014). "In the growth of embryonic stem cells and cancer stem cells, EGF is crucial to maintain the stemness." (PMID 25003232, 2014). "EGF is a low-molecular-weight polypeptide which affects many biochemical pathways by binding to its receptor and can be used as a cancer biomarker." (PMID 25326050, 2014). "This is the first report of regulation of RGS16 by pRb and RGS16-mediated inhibition of EGF-induced migration and invasion in normal and cancer cells." (PMID 25568667, 2014). "Our results suggest that B4GALNT3 plays a role in regulating cancer stem like cell property via the EGF/EGFR pathway." (PMID 25003232, 2014). "We have tracked the dynamics of PTPD1, a positive regulator of EGF signalling over expressed in cancer cells." (PMID 25062045, 2014). "FN-β1 integrin signal was also found to synergistically enhance STAT3 activation induced by EGF and IL-6 in breast or other cancer cells." (PMID 25327561, 2014). "EGF and IGFs are critical regulators of cell differentiation, survival, proliferation, and migration in cancers." (PMID 24618737, 2014). "Blocking the binding of EGF to EGFR can abolish cancer proliferation, invasion, metastasis, angiogenesis and inhibition of apoptosis." (PMID 25386651, 2014). "Blood group antigens are present on key receptors, which differ according to the cancer type, and control cell proliferation, resistance to apoptosis and adhesion, such as receptors for integrins, cadherins, epidermal growth factor and CD44." (PMID 24516588, 2014). "Our present study provides evidence that EGF plays an initial role in the development of the cancer inflammation and in the promotion of cancer cells from low metastatic potentials into high metastatic potential." (PMID 24268047, 2014). "Positive Ki-67 labeling was observed in 91% of MDA-MB-231 cancer cells grown in control media containing 20 ng/mL of EGF after a 72-h culture period." (PMID 24736807, 2014). "This is important because EGF/EGFR axis is known to regulate cancer cells to proliferate and migrate to distant sites." (PMID 24811863, 2014).